FLOT2 (flotillin 2)
Description:
May act as a scaffolding protein within caveolar membranes, functionally participating in formation of caveolae or caveolae-like vesicles. May be involved in epidermal cell adhesion and epidermal structure and function.
Synonyms: ESA; ESA1; M17S1; ECS-1; ECS1
Tractability: Antibody: UniProt places it where antibodies can reach, with high confidence; its Gene Ontology location is reachable by antibodies, with high confidence; the Human Protein Atlas places it where antibodies can reach. PROTAC: ubiquitination databases record sites on it; its protein half-life has been measured.
Gene: Protein-coding gene on chromosome 17 (28,879,335 to 28,897,739, reverse strand). Ensembl gene ENSG00000132589.
Subcellular location: Cell membrane; Membrane, caveola; Endosome; Membrane
Subcellular location (Human Protein Atlas): Plasma membrane; Vesicles
Pathways (Reactome):
Signal Transduction: RHOA GTPase cycle; RHOB GTPase cycle; RHOC GTPase cycle; RND1 GTPase cycle; RND3 GTPase cycle
Programmed Cell Death: RIPK1-mediated regulated necrosis; Regulation of necroptotic cell death
Neuronal System: Synaptic adhesion-like molecules
Gene Ontology:
Molecular function: protein binding; protease binding
Biological process: negative regulation of amyloid precursor protein catabolic process; negative regulation of gene expression; positive regulation of canonical NF-kappaB signal transduction; positive regulation of establishment of T cell polarity; protein localization to plasma membrane; protein localization to plasma membrane raft; protein stabilization; regulation of myoblast differentiation; cell adhesion; epidermis development; anterograde dendritic transport; regulation of postsynaptic membrane neurotransmitter receptor levels
Cellular component: adherens junction; apical plasma membrane; basolateral plasma membrane; caveola; cell-cell contact zone; cortical actin cytoskeleton; cytoplasmic vesicle; endocytic vesicle; endosome; extracellular exosome; flotillin complex; focal adhesion; lamellipodium; membrane; perinuclear region of cytoplasm; plasma membrane; uropod; vesicle; acrosomal membrane; dendrite cytoplasm; glutamatergic synapse; membrane raft
Genetic constraint (gnomAD): Loss-of-function variants: 33 observed, 55.83 expected, observed/expected ratio (o/e) 0.59, 90% interval 0.45 to 0.79. The upper end of that interval is the gene's LOEUF score, 0.79, which puts it in group 3 of 6, group 1 being the genes least tolerant of losing a copy. Missense variants: 464 observed, 591.13 expected, observed/expected ratio (o/e) 0.78, 90% interval 0.73 to 0.85. Synonymous variants: 207 observed, 235.63 expected, observed/expected ratio (o/e) 0.88, 90% interval 0.78 to 0.99.
Homologues: Orthologues: chimpanzee FLOT2 (100% identical), macaque FLOT2 (100% identical), dog FLOT2 (99% identical), mouse Flot2 (99% identical), guinea pig FLOT2 (99% identical), rabbit FLOT2 (98% identical), rat Flot2 (97% identical), pig FLOT2 (96% identical), tropical clawed frog flot2 (82% identical), zebrafish flot2b (81% identical), zebrafish flot2a (81% identical), Drosophila melanogaster Flo2 (65% identical), and 1 more. Paralogues in human: FLOT1 (47% identical).
Diseases named in the same sentence as FLOT2 in open-access papers:
FLOT2 is named in the same sentence as 71 diseases in open-access papers, as found by Europe PMC text mining. Sharing a sentence is not in itself a finding about the gene and the disease. The quoted sentences say what the papers report.
breast carcinoma (22 papers, 2013 to 2026). "SMS2 increased the expression of lipid-raft-associated FLOT2 by upregulating SM, which subsequently activated the NF-κB signaling pathway and promoted cell stemness of breast cancer cells, thus increasing the drug resistance toward ADR." (PMID 38285090, 2024). "Recently, it is reported that over-expression of Flot-2 is associated with poor prognosis and reduced survival of breast cancer patients with both early-and late-stage." (PMID 25014228, 2014). "Overexpression of flotillin-2 in breast cancer was shown to be associated with the clinical stage, T and M classification, histological differentiation and receptor tyrosine kinase ErbB2 expression levels." (PMID 24709906, 2014). "Flot-2 deficiency leads to a striking reduction in the number of lung metastasis, so they think that Flot-2 is an important regulator of mammary tumor-derived lung metastasis." (PMID 25014228, 2014). "In this report, we present new evidence that the overexpression of FLOT2 is associated with poor prognosis in breast cancer patients with both early- and late-stage disease." (PMID 23945257, 2013). "The FLOT2-mediated stabilization of ErbB2 has been associated with tumorigenesis in stage I/II breast cancer tissues, which is reflected by reduced p-ErbB2 and p-Akt levels and hyperactivity of the PI3K/AKT/mTOR pathway in breast tumors." (PMID 23945257, 2013). "The current results demonstrated that high FLOT2 protein expression was associated with poor outcomes in patients with breast cancer." (PMID 23945257, 2013). "Moreover, the overexpression of FLOT2 in breast cancer is associated with the clinical stage, T and M classification, histological differentiation and ErbB-2 expression levels." (PMID 23945257, 2013). "Overexpression of FLOT2 exacerbates the proliferation and epithelial/mesenchymal transition of cervical cancer cells, while silencing of FLOT2 attenuated p-AKT in breast cancer cells." (PMID 40429638, 2025). "Our findings demonstrated that SMS2 upregulated the lipid raft marker protein FLOT2 in breast cancer cells." (PMID 38285090, 2024). "As a regulator of lung metastasis, decreased expression of FLOT2 protein reduces the tumorigenic and metastatic ability of human breast cancer cell lines in vivo." (PMID 38285090, 2024). "FLOT2 is overexpressed and correlated with significantly worse prognosis in a variety of types of malignant tumors, including breast cancer, melanoma, stomach cancer, cervical cancer and nasopharyngeal cancer." (PMID 38285090, 2024). "FLOT2, known as an LR marker protein, closely correlates with the stage and prognosis of breast cancer." (PMID 38285090, 2024). "For instance, the tyrosine kinase ErbB2, which is overexpressed in several breast cancers, is internalized and degraded upon knockdown of flotillin-1 or flotillin-2." (PMID 32314087, 2020). "To evaluate the effect of 4-cholesten-3-one on the membrane rafts of breast cancer cells, we first studied the protein expression of flotillin-2, a membrane raft marker." (PMID 31477154, 2019). "Migration of tumor cells is a prerequisite for the formation of metastases, and flotillin-2 knockout has been shown to impair metastasis formation in a breast cancer mouse model." (PMID 29642469, 2018). "In particular, flotillin-2 emerged as a potential predictor of prognosis in HER2-amplified breast cancer." (PMID 29657291, 2017). "In line with this, the gene for flotillin-2 is located in a region on human chromosome 17q11.2 that is commonly amplified in human breast cancers." (PMID 24709906, 2014). "Reduction of Flot-2 protein levels significantly reduced the tumorigenicity and metastatic capability of a human breast cancer cell line in vivo." (PMID 25014228, 2014).
breast carcinoma (continued). "We further analyzed the relationship between the expression of FLOT2 and clinical characteristics of patients affected by breast cancer." (PMID 23945257, 2013). "As many pathways have been reported to be hyperactive in breast tumors, the protein kinases located along the pathway regulated by FLOT2 represent attractive drug targets for breast cancer therapies." (PMID 23945257, 2013). "In the present study, we found that the expression of FLOT2 was upregulated in breast cancer cells and surgical specimens of breast cancer." (PMID 23945257, 2013). "Our results suggest the important role of FLOT2 protein in the prognosis of patients with breast cancer." (PMID 23945257, 2013). "Higher FLOT2 expression levels are a significant prognostic marker of poor survival in breast cancer patients." (PMID 23945257, 2013). "Multivariate analysis suggested that FLOT2 expression was an independent prognostic marker for survival in patients with breast cancer." (PMID 23945257, 2013). "In conclusion, this is the first study to highlight the clinical significance of FLOT2 in breast cancer." (PMID 23945257, 2013). "FLOT2 protein expression was analyzed in 171 archived paraffin-embedded breast cancer samples using immunohistochemistry (IHC)." (PMID 23945257, 2013). "To evaluate the expression levels of FLOT2 protein and mRNA in breast cancer cell lines, we used Western blotting and real-time RT-PCR." (PMID 23945257, 2013). "A comprehensive analysis of the molecular mechanism of FLOT2 involvement in the development and progression of breast cancer is eagerly awaited." (PMID 23945257, 2013). "FLOT2 was significantly upregulated in breast cancer cell lines and tissue samples compared with normal cells and adjacent noncancerous breast tissues, respectively." (PMID 23945257, 2013). "IHC analyses indicated that FLOT2 was highly expressed in breast cancer tissues, which was significantly correlated with the clinical stage of the disease and unfavorable survival durations." (PMID 23945257, 2013). "Our study aimed to investigate the expression pattern and clinicopathological significance of FLOT2 in patients with breast cancer." (PMID 23945257, 2013). "Our results clearly showed that the upregulation of FLOT2 occurred at both the levels of mRNA and protein in breast cancer cell lines compared to NMEC." (PMID 23945257, 2013). "Taken together, our results suggest that FLOT2 plays a significant role in the development and progression of human breast cancer." (PMID 23945257, 2013). "Shortly afterwards, FLOT2 was reported as a significant regulator of mammary tumor-derived lung metastasis." (PMID 23945257, 2013). "Data from a very recent publication of the genetic ablation of FLOT2 in a well-established mouse model of mammary tumorigenesis and metastasis indicated that FLOT2 predicts mammary tumor-derived lung metastasis." (PMID 23945257, 2013). "FLOT2 overexpression is reported to be associated with the tumor grade, TNM stage, distant metastasis in multiple malignancies and can be useful as a prognostic biomarker for breast cancer progression." (PMID 38285090, 2024). "Interestingly, tissue microarray analysis of biopsies from almost 200 breast cancer patients showed that flotillin-2 is a potential predictor of prognosis in breast cancer patients." (PMID 32314087, 2020). "Western blotting performed following membrane raft isolation revealed reduced expression of flotillin-2 in the membrane raft fractions of the two treated breast cancer cells, attesting that 4-cholesten-3-one could disrupt the integrity of membrane rafts." (PMID 31477154, 2019). "Studies on flotillin-2 knockout mice interbred with a breast cancer mouse model, MMTV-PyMT (mouse mammary tumor virus-polyoma middle T antigen) mice, showed that flotillins might be important especially for the formation of metastases." (PMID 29642469, 2018). "The pro-metastatic role of Flot-2 was demonstrated in a mouse breast cancer model." (PMID 26206082, 2015).
breast carcinoma (continued). "Furthermore, reduced Flot-2 expression was shown to result in a reduction in lung metastases of breast cancer in a mouse breast cancer model." (PMID 26206082, 2015). "Furthermore, IHC staining showed that FLOT2 expression in breast cancer increased with advancing clinical stage." (PMID 23945257, 2013). "In contrast, FLOT2 was highly expressed in breast cancer tissues." (PMID 23945257, 2013). "To determine whether FLOT2 is also high-expressed in the human breast cancer clinical samples, we performed RT-PCR and Western blotting analyses on four breast tumor samples (T) matched with adjacent noncancerous tissue samples (ANT)." (PMID 23945257, 2013). "Multivariate analysis revealed that FLOT2 might be an independent biomarker for the prediction of breast cancer prognosis." (PMID 23945257, 2013). "IHC analysis revealed high expression levels of FLOT2 in 82 of 171 (48.0%) breast cancer specimens." (PMID 23945257, 2013). "Multivariate analysis revealed that FLOT2 expression might be an independent prognostic indicator of survival in breast cancer patients." (PMID 23945257, 2013). "Multivariate analysis showed that FLOT2 protein levels could be used as an independent prognostic predictor for breast cancer patients." (PMID 23945257, 2013). "In breast cancer, increased flotillin-2 levels correlate with reduced patient survival." (PMID 24304721, 2013). "Further investigation is also needed to determine whether FLOT2 could be identified as a target for novel therapeutics against breast cancer." (PMID 23945257, 2013). "However, further studies are required to obtain a detailed picture of FLOT2-related signaling pathways in breast cancer development." (PMID 23945257, 2013). "Thus, Flot-2 knockout inhibits lung metastasis in a breast cancer mouse model." (PMID 26206082, 2015). "Also, increased expression of Flot-2 is associated with poor outcomes in patients with several solid tumors, such as breast cancer, gastric cancer and cervical carcinoma, and Flot-2 could be used as a prognostic biomarker for these tumors progression." (PMID 26161893, 2015). "FLOT2 could be used as a prognostic biomarker for breast cancer progression." (PMID 23945257, 2013). "We therefore hypothesize that FLOT2 may affect the development and progression of breast cancer through modulating certain signaling pathways, which may open new avenues into the treatment of breast cancer." (PMID 23945257, 2013). "On the other hand, low expression of TTF2, ABCC2, FLOT2, and NLRP2 was correlated with poor prognosis in HER2-positive breast cancer patients, whereas their low expression was correlated with better prognosis in the overall METABRIC cohort." (PMID 32640677, 2020). "However, the clinical significance of FLOT2 in breast cancer remains unclear." (PMID 23945257, 2013). "To study the function of flotillins in breast cancer cells, we generated human MCF7 cell lines in which flotillin-1 or flotillin-2 expression was stably knocked down by means of lentivirus mediated short hairpin RNAs (shRNAs)." (PMID 24304721, 2013). "However, breeding of the flotillin-2 knockout mouse with an established breast cancer mouse model showed that the formation of lung metastases was significantly reduced upon flotillin ablation, implicating a functional role for flotillins in migratory processes during breast cancer progression." (PMID 24391950, 2013). "FLOT2 protein was highly expressed in breast cancer cell lines and only weakly expressed in NMEC, and FLOT2 mRNA expression was expressed by at least 5-fold higher levels in breast cancer cell lines compared to NMEC." (PMID 23945257, 2013). "In an ErbB2 overexpressing breast cancer cell line, SKBR3, flotillin-1 and flotillin-2 partially colocalized with ErbB2 at the plasma membrane and formed a complex with ErbB2 and Hsp90 which is an important factor for the stabilization of ErbB2 at the plasma membrane." (PMID 24709906, 2014).
breast carcinoma (continued). "The expression of FLOT2 mRNA and protein were determined for eight breast cancer cell lines (BT-549, MDA-MB-468, MDA-MB-453, Bcap37, MCF-7, T47D, ZR-75-1 and MDA-MB-231) and compared with FLOT2 expression in primary cultured normal mammary epithelial cells (NMEC)." (PMID 23945257, 2013). "FLOT2 mRNA was expressed at higher levels in all breast cancer tissues than in adjacent noncancerous tissues, with the differential expression level ranging from 5.1- to 24.4-fold." (PMID 23945257, 2013). "The expression level of FLOT2 in normal breast epithelial cells, breast cancer cell lines, and four breast cancer biopsies paired with adjacent noncancerous tissues were quantified using real-time RT-PCR and Western blotting." (PMID 23945257, 2013). "In the SKBR3 breast cancer cells, the result that Akt phosphorylation is reduced upon depletion of flotillin-2, but not after flotillin-1 knockdown, agreed with our data." (PMID 23658725, 2013). "Interestingly, previous studies have suggested that elevated flotillin-2 expression in gastric cancers correlates with ErbB2 levels, and flotillins are required to stabilize ErbB2 in the plasma membrane in SKBR3 breast cancer cells." (PMID 24304721, 2013). "However, another study suggested that flotillin-2 but not flotillin-1 expression can be used as a prognostic marker for relapse in breast cancer in patients of stage I/II." (PMID 24709906, 2014). "Furthermore, the same study demonstrated that flotillin-2 is up-regulated on protein and mRNA level in various breast cancer cell lines as well as in breast cancer tissues in comparison with adjacent non-cancerous tissue samples." (PMID 24709906, 2014). "Paired breast cancer lesions and adjacent noncancerous tissues were found to have different expression levels of FLOT2, with cancer lesions displaying relatively higher expression levels of FLOT2." (PMID 23945257, 2013). "It was shown that overexpressing Flot2 transformed the nontumorigenic and nonmetastatic melanoma SB2 cells into highly tumorigenic and metastatic cells, while Flot2 deficiency leads to the deletion of plain raft and significant reduction of lung metastasis in breast cancer cells." (PMID 25909165, 2015). "Therefore, testing the FLOT2 protein level may be useful for stratifying patients for novel therapeutic strategies and establishing rational treatment selection criteria for patients with breast cancer." (PMID 23945257, 2013). "Patient survival analysis showed a clear negative correlation between the level of FLOT2 protein expression and both the OS and 5-year DFS of patients with breast cancer (both P < 0.001)." (PMID 23945257, 2013).